UBE2S (ubiquitin conjugating enzyme E2 S)
Description:
Accepts ubiquitin from the E1 complex and catalyzes its covalent attachment to other proteins. Catalyzes 'Lys-11'-linked polyubiquitination. Acts as an essential factor of the anaphase promoting complex/cyclosome (APC/C), a cell cycle-regulated ubiquitin ligase that controls progression through mitosis. Acts by specifically elongating 'Lys-11'-linked polyubiquitin chains initiated by the E2 enzyme UBE2C/UBCH10 on APC/C substrates, enhancing the degradation of APC/C substrates by the proteasome and promoting mitotic exit. Also acts by elongating ubiquitin chains initiated by the E2 enzyme UBE2D1/UBCH5 in vitro; it is however unclear whether UBE2D1/UBCH5 acts as an E2 enzyme for the APC/C in vivo. Also involved in ubiquitination and subsequent degradation of VHL, resulting in an accumulation of HIF1A. In vitro able to promote polyubiquitination using all 7 ubiquitin Lys residues, except 'Lys-48'-linked polyubiquitination.
Synonyms: E2EPF; E2-EPF; EPF5
Tractability: Small molecule: a structure with a bound ligand is known. Antibody: the Human Protein Atlas places it where antibodies can reach. PROTAC: UniProt records ubiquitination sites on it; ubiquitination databases record sites on it.
Target class: Enzyme; Transferase
Gene: Protein-coding gene on chromosome 19 (55,399,745 to 55,407,788, reverse strand). Ensembl gene ENSG00000108106.
Subcellular location (Human Protein Atlas): Plasma membrane; Nucleoplasm
Pathways (Reactome):
Cell Cycle: APC-Cdc20 mediated degradation of Nek2A; APC/C:Cdc20 mediated degradation of Cyclin B; APC/C:Cdc20 mediated degradation of Securin; APC/C:Cdc20 mediated degradation of mitotic proteins; APC/C:Cdh1 mediated degradation of Cdc20 and other APC/C:Cdh1 targeted proteins in late mitosis/early G1; Autodegradation of Cdh1 by Cdh1:APC/C; Cdc20:Phospho-APC/C mediated degradation of Cyclin A; Conversion from APC/C:Cdc20 to APC/C:Cdh1 in late anaphase; Inactivation of APC/C via direct inhibition of the APC/C complex; Phosphorylation of the APC/C; Regulation of APC/C activators between G1/S and early anaphase; Separation of Sister Chromatids
DNA Replication: Assembly of the pre-replicative complex; CDK-mediated phosphorylation and removal of Cdc6
Cellular responses to stimuli: Senescence-Associated Secretory Phenotype (SASP)
Disease: Aberrant regulation of mitotic exit in cancer due to RB1 defects
Gene expression (Transcription): Transcriptional Regulation by VENTX
Immune System: Antigen processing: Ubiquitination & Proteasome degradation
Metabolism of proteins: Synthesis of active ubiquitin: roles of E1 and E2 enzymes
Gene Ontology:
Molecular function: anaphase-promoting complex binding; protein binding; ubiquitin conjugating enzyme activity; ubiquitin-protein transferase activity; ubiquitin-like protein transferase activity
Biological process: anaphase-promoting complex-dependent catabolic process; exit from mitosis; free ubiquitin chain polymerization; positive regulation of ubiquitin protein ligase activity; proteasome-mediated ubiquitin-dependent protein catabolic process; protein K11-linked ubiquitination; protein K27-linked ubiquitination; protein K29-linked ubiquitination; protein K6-linked ubiquitination; protein K63-linked ubiquitination; protein modification process; protein polyubiquitination; protein modification by small protein conjugation; protein ubiquitination
Cellular component: anaphase-promoting complex; cytosol; nucleoplasm
Genetic constraint (gnomAD): Loss-of-function variants: 3 observed, 10.31 expected, observed/expected ratio (o/e) 0.29, 90% interval 0.13 to 0.75. The upper end of that interval is the gene's LOEUF score, 0.75, which puts it in group 3 of 6, group 1 being the genes least tolerant of losing a copy. Missense variants: 150 observed, 242.64 expected, observed/expected ratio (o/e) 0.62, 90% interval 0.54 to 0.71. Synonymous variants: 105 observed, 109.67 expected, observed/expected ratio (o/e) 0.96, 90% interval 0.82 to 1.13.
Homologues: Orthologues: chimpanzee UBE2S (99% identical), macaque UBE2S (99% identical), pig UBE2S (97% identical), dog UBE2S (95% identical), rat Ube2s (94% identical), mouse Ube2s (93% identical), mouse Ube2srt (92% identical), guinea pig UBE2S (91% identical), rabbit UBE2S (88% identical), tropical clawed frog ube2s (76% identical), zebrafish ube2s (69% identical), Drosophila melanogaster CG8188 (57% identical). Paralogues in human: UBE2O (28% identical), UBE2N (25% identical), UBE2NL (24% identical), UBE2Z (23% identical), CDC34 (22% identical), UBE2R2 (21% identical), UBE2B (21% identical), UBE2I (21% identical), UBE2K (21% identical), UBE2T (21% identical), UBE2A (20% identical), UBE2C (19% identical), and 12 more.
Diseases named in the same sentence as UBE2S in open-access papers:
UBE2S is named in the same sentence as 60 diseases in open-access papers, as found by Europe PMC text mining. Sharing a sentence is not in itself a finding about the gene and the disease. The quoted sentences say what the papers report.
hepatocellular carcinoma (15 papers, 2020 to 2024). A malignant tumor that arises from hepatocytes. "The transcription factor FOXM1 induces the upregulation of UBE2S in hepatocellular carcinoma cells, leading to the ubiquitination of PTEN at Lys327, Lys 60 and the phosphorylation of AKT, which enhances chemoresistance." (PMID 38312603, 2024). "The induction of UBE2S in hepatocellular carcinoma cells is attributed to the transcription factor FOXM1." (PMID 38312603, 2024). "The abnormally high expression of UBE2S was found to promote resistance of hepatocellular carcinoma cells to oxaliplatin and 5-FU via the FOXM1/UBE2S/PTEN/p/AKT axis." (PMID 38312603, 2024). "This preliminary elucidation of the role of UBE2S in chemotherapy resistance in hepatocellular carcinoma provides valuable insight." (PMID 38312603, 2024). "The upregulation of UBE2S was observed to enhance the G1/S phase transition, metastasis, invasion, and proliferation of hepatocellular carcinoma cells, and to significantly augment tumor growth in animals." (PMID 38312603, 2024). "The findings of the study indicate that in the nucleus, overexpression of TRIM28 and UBE2S facilitates p27 ubiquitination, thereby promoting the G1/S phase transition of hepatocellular carcinoma cells and ultimately leading to cell cycle progression." (PMID 38312603, 2024). "UBE2S, overexpressed in hepatocellular carcinoma(HCC), interacted with TRIM28 in the nucleus to jointly enhance the ubiquitination of p27 and promoted its degradation and cell cycle progression." (PMID 36756159, 2023). "Studies have shown that UBE2S accelerates the cell cycle and promotes the development of hepatocellular carcinoma through the ubiquitination of p27." (PMID 35658829, 2022). "In a previous study, cephalomannine, as a natural compound, was reported to inhibit UBE2S in hepatocellular carcinoma (HCC) in a dose-dependent manner by suppressing its promoter activity." (PMID 35637955, 2022). "To summarize, UBE2S serves as a biomarker for prognosticating hepatocellular carcinoma." (PMID 38312603, 2024). "UBE2S is overexpressed in tumors, including hepatocellular carcinoma (HCC)." (PMID 37563971, 2023). "Notably, in vitro functional validation showed that UBE2S knockdown attenuated the phenotypes of proliferation, clonogenicity, and migration in hepatocellular carcinoma cells." (PMID 35578600, 2022). "In addition, UBE2S accelerated the cell cycle by ubiquitination of p27 to promote hepatocellular carcinoma development." (PMID 35637955, 2022). "In addition, the FOXM1/UBE2S/PTEN/p/AKT axis it participates in may become a potential therapeutic direction for hepatocellular carcinoma." (PMID 38312603, 2024). "UBE2S, which is found to be overexpressed in hepatocellular carcinoma (HCC), interacts with TRIM28 in the nucleus, together promoting the ubiquitination of P27." (PMID 39534556, 2024). "Most importantly, many studies have reported that UBE2S may promote the malignant progression of hepatocellular carcinoma, non-small cell lung cancer, lung adenocarcinoma, and even endometrial cancer by promoting cell proliferation and other malignant biological processes, leading to poor prognosis." (PMID 35658829, 2022).
hepatocellular carcinoma (continued). "UBE2S is responsible for ubiquitinating PTEN at phosphorylating AKT and Lys327, as well as Lys 60, which results in an increase in chemoresistance in hepatocellular carcinoma cells." (PMID 38312603, 2024). "Moreover, UBE2S is highly expressed in hepatocellular carcinoma (HCC), where it interacts with TRIM28 and enhances ubiquitination of p27, thus promoting HCC progression." (PMID 34123793, 2021). "The malignant phenotype of hepatocellular carcinoma could be promoted by the FOXM1/UBE2S/PTEN/p/AKT axis, indicating that it may be possible to treat this disease by targeting UBE2S." (PMID 38312603, 2024). "Additionally, the activation of H3K4me3 was found to be necessary for the UBE2S promoter to bind to FOXM1 and activate UBE2S transcription in hepatocellular carcinoma, thereby increasing resistance to oxaliplatin and 5-FU." (PMID 38312603, 2024). "Ubiquitin conjugating enzyme E2S (UBE2S), a well-established k11 linkage-specific E2 corresponding to a 24 kDa peptide, was reported to produce aberrantly higher expression and poor outcomes in multiple human cancers such as colorectal cancer (CRC), glioma, and hepatocellular carcinoma (HCC)." (PMID 35578600, 2022).
breast carcinoma (14 papers, 2014 to 2025). "The study revealed that UBE2S exhibited a significant upregulation in breast cancer, which was correlated with advanced tumor staging and unfavorable prognosis." (PMID 38312603, 2024). "Taken together, the results of this study suggest that UBE2S represents a promising research direction of breast cancer." (PMID 38312603, 2024). "Specifically, this investigation reveals that the ubiquitin-coupled enzyme E2S (UBE2S) is markedly upregulated in breast cancer and exerts a modulatory effect on the phosphorylation of FAK at Tyr397, thereby impeding integrin signaling." (PMID 38312603, 2024). "In other words, high levels of UBE2S and UBE2C and decreased Numb expression were associated with a shorter lifespan in breast cancer patients." (PMID 36860312, 2023). "A better understanding of the regulatory mechanisms underlying UBE2S and UBE2C function in breast cancer is expected to identify novel prognostic markers and develop new effective anticancer strategies." (PMID 36860312, 2023). "Breast cancer with higher UBE2S or UBE2C levels and lower Numb expression is correlated with a worse prognosis, providing potential biomarkers for BC therapeutics." (PMID 36860312, 2023). "In a paired analysis of breast cancer and adjacent normal tissue, higher levels of UBE2S and UBE2C and lower Numb expression were found in the former." (PMID 36860312, 2023). "Compared with ER+ breast cancer cell lines, ER− cells demonstrated higher UBE2S and UBE2C alongside lower Numb, also in line with transcriptomic results." (PMID 36860312, 2023). "In breast cancer, it has been reported that inhibition of UBE2S or UBE2C suppressed the malignant characteristics of breast cancer cells and sensitized cancer cells to radiation or drugs to enhance clinical effectiveness." (PMID 36860312, 2023). "Compared with PR+ breast cancer, the mRNA levels of UBE2S and UBE2C were higher, while NUMB was lower in PR− breast cancer." (PMID 36860312, 2023). "Knockdown of UBE2S expression increased the sensitivity of breast cancer and glioblastoma cells to etoposide." (PMID 37563971, 2023). "Silencing UBE2S in different breast cancer cell lines resulted in inhibiting proliferation, facilitating apoptosis, and altering the morphology of these cells, thus indicating a role for UBE2S in tumorigenesis." (PMID 34199813, 2021). "In breast cancer cells, UBE2S—coupled with the Ub ligase, anaphase-promoting complex/cyclosome (APC/C)—enhances the degradation of substrate proteins via the proteasome pathway during mitosis to promote the exit of cells from the mitotic stage." (PMID 34199813, 2021). "Furthermore, we demonstrate that UBE2S depletion effectively suppresses the breast cancer cell biological behavior, including anchorage-independent growth, invasion, and migration." (PMID 38312603, 2024). "Besides, we resorted to the Oncomine datasets regarding breast cancer and found that there was evidently higher mRNA expression of UBE2S and UBE2C but lower Numb expression in breast cancer samples than their respective normal controls." (PMID 36860312, 2023). "However, a significant increase in Numb expression was observed by silencing UBE2S or UBE2C expression in breast cancer cells at both protein and mRNA levels." (PMID 36860312, 2023). "Recently, UBE2S was shown to mediate chemoresistance in breast cancer and glioblastoma." (PMID 37563971, 2023). "These suggested that HECTD3, PSMB10, UBD, UBE2C, and UBE2S might also affect the efficacy of neoadjuvant chemotherapy in breast cancer through the ubiquitin proteasome pathway." (PMID 29685151, 2018). "In a recent work in breast cancer authors identified, through weighted gene co-expression network analysis, a cluster of proliferation-related genes including UBE2S that, when up-regulated, were correlated to increased tumor grade and were associated with poor survival." (PMID 24748173, 2014). "Moreover, UBE2S overexpression was found to promote malignant phenotypes in breast cancer cells." (PMID 38312603, 2024).
breast carcinoma (continued). "Therefore, we propose that combining UBE2S or UBE2C with Numb may serve as an effective predictor of breast cancer survival." (PMID 36860312, 2023). "In addition, we found that overexpression of UBE2S or UBE2C led to increased capabilities of colony formation and cell proliferation while silencing of UBE2S or UBE2C displayed opposite trends in breast cancer cells, indicating the tumor-promoting effect of elevated UBE2S or UBE2C expression." (PMID 36860312, 2023). "UBE2S is correlated with the malignant characteristics (such as anchorage-independent growth, migration, and invasion) of breast cancer cells, and thus, UBE2S may be used as a therapeutic target for breast cancer." (PMID 29685151, 2018). "UBE2S is identified simultaneously with HIF‐1α in human primary hepatic, colon, and breast cancers, metastatic cholangiocarcinoma, and cells of colon cancer." (PMID 41427004, 2025). "UBE2S was overexpressed in many tumors, such as ESCC, oral squamous cell cancer, gastric malignancy, and breast cancer." (PMID 41427004, 2025). "By using Oncomine data analysis and Kaplan–Meier plotter survival analysis, we further analyzed the prognostic effects of UBE2S, UBE2C, and Numb in breast cancer patients." (PMID 36860312, 2023). "To identify the differential expression of UBE2S, UBE2C, and Numb in breast cancer tissues at the protein level, we resorted to the Human Protein Atlas (HPA) database." (PMID 36860312, 2023). "Taken together, these results revealed an overexpression of both UBE2S and UBE2C and a downregulation of Numb in breast cancer, indicating the oncogenic effects of UBE2S and UBE2C and the tumor suppressive role of Numb in breast cancer." (PMID 36860312, 2023). "Given above, the expression and prognostic roles of UBE2S, UBE2C, and Numb were evaluated in breast cancer as well as in ER+ breast cancer in this research." (PMID 36860312, 2023). "The expression of UBE2S and UBE2C was decreased and Numb was increased in ER+ breast cancer; we thus explored the prognostic values of UBE2S, UBE2C, and Numb in ER+ breast cancer patients." (PMID 36860312, 2023). "Taken together, we uncover that UBE2S and UBE2C confer a poor prognosis for breast cancer via downregulation of Numb." (PMID 36860312, 2023). "To explore the functional role of UBE2S, UBE2C, and Numb in ER+ breast cancer, we compared the mRNA levels of the three genes in ER+ and ER− breast cancer through Oncomine dataset analysis." (PMID 36860312, 2023). "We also sought to determine the correlation between UBE2S, UBE2C, and Numb expression in three common types of breast cancer, namely ER+, HER2+, and triple-negative breast cancer (TNBC)." (PMID 36860312, 2023). "Next, we evaluated the impact of differential mRNA expression of UBE2S, UBE2C, and Numb on the clinical survival of breast cancer patients." (PMID 36860312, 2023). "Next, we found that the expression of UBE2S and UBE2C was upregulated while Numb was downregulated in breast cancer tissues of higher histological grades and pathological stages." (PMID 36860312, 2023). "We reported overexpression of UBE2S and UBE2C and downregulation of Numb in breast cancer compared with normal breast tissue at both mRNA and protein levels." (PMID 36860312, 2023). "Compared with ER+ breast cancer, the mRNA levels of UBE2S and UBE2C were higher, while NUMB was reduced in ER− breast cancer." (PMID 36860312, 2023). "UBE2S and UBE2C also demonstrated increased expression in breast cancer with a more advanced grade and stage, while Numb showed the opposite trend." (PMID 36860312, 2023). "Increased expression of UBE2S and UBE2C predicted worse OS and RFS, while increased Numb expression was related to a better outcome in ER+ breast cancer patients." (PMID 36860312, 2023). "In the present study, we first proposed that UBE2S and UBE2C confer poor prognosis in breast cancer via downregulation of Numb." (PMID 36860312, 2023).